KIF5C (kinesin family member 5C)
Description:
Microtubule-associated force-producing protein that may play a role in organelle transport. Has ATPase activity (By similarity). Involved in synaptic transmission. Mediates dendritic trafficking of mRNAs (By similarity). Required for anterograde axonal transportation of MAPK8IP3/JIP3 which is essential for MAPK8IP3/JIP3 function in axon elongation (By similarity).
Synonyms: NKHC2; CDCBM2; KINN; NKHC; NKHC-2
Tractability: PROTAC: ubiquitination databases record sites on it; its protein half-life has been measured.
Target class: Other cytosolic protein
Gene: Protein-coding gene on chromosome 2 (148,875,227 to 149,026,759, forward strand). Ensembl gene ENSG00000168280.
Subcellular location: Cytoplasm, cytoskeleton; Cell projection, dendrite
Subcellular location (Human Protein Atlas): Connecting piece; Cytosol; Equatorial segment
Pathways (Reactome):
Metabolism of proteins: Insulin processing
Gene Ontology:
Molecular function: protein binding; ATP hydrolysis activity; microtubule motor activity; plus-end-directed microtubule motor activity; apolipoprotein receptor binding; ATP binding; microtubule binding
Biological process: anterograde axonal protein transport; anterograde dendritic transport of neurotransmitter receptor complex; axon guidance; mRNA transport; organelle organization; synaptic vesicle transport; anterograde dendritic transport of messenger ribonucleoprotein complex; intracellular mRNA localization; microtubule-based movement
Cellular component: axonal growth cone; distal axon; kinesin complex; neuronal cell body; axon cytoplasm; ciliary rootlet; cytoplasm; cytoskeleton; dendrite; dendrite cytoplasm; GABA-ergic synapse; neuron projection; postsynaptic cytosol
Genetic constraint (gnomAD): Loss-of-function variants: 17 observed, 102.26 expected, observed/expected ratio (o/e) 0.17, 90% interval 0.11 to 0.25. The upper end of that interval is the gene's LOEUF score, 0.25, which puts it in group 1 of 6, group 1 being the genes least tolerant of losing a copy. Missense variants: 740 observed, 1,064.1 expected, observed/expected ratio (o/e) 0.7, 90% interval 0.65 to 0.74. Synonymous variants: 379 observed, 382.23 expected, observed/expected ratio (o/e) 0.99, 90% interval 0.91 to 1.08.
Gene-disease validity (ClinGen):
ClinGen rates the evidence that KIF5C causes each of these diseases.
complex cortical dysplasia with other brain malformations 2 (autosomal dominant): Moderate.
Homologues: Orthologues: chimpanzee KIF5C (100% identical), macaque KIF5C (99% identical), guinea pig KIF5C (99% identical), pig KIF5C (99% identical), mouse Kif5c (98% identical), rabbit KIF5C (98% identical), rat Kif5c (98% identical), dog KIF5C (93% identical), tropical clawed frog kif5c (89% identical). Paralogues in human: KIF5B (76% identical), KIF5A (75% identical), KIF21A (26% identical), KIF21B (26% identical), CENPE (26% identical), KIF27 (25% identical), KIF7 (25% identical), KIF15 (25% identical), KIF11 (24% identical), KIF4B (24% identical), KIF4A (24% identical), KIF13A (23% identical), and 29 more.
Diseases named in the same sentence as KIF5C in open-access papers:
KIF5C is named in the same sentence as 77 diseases in open-access papers, as found by Europe PMC text mining. Sharing a sentence is not in itself a finding about the gene and the disease. The quoted sentences say what the papers report.
hereditary spastic paraplegia (6 papers, 2011 to 2024). Hereditary spastic paraplegias (HSP) comprise a genetically and clinically heterogeneous group of neurodegenerative disorders characterized by progressive spasticity and hyperreflexia of the lower limbs. "The extensive repertoire of kinesin families, especially the KIF5 family (comprising KIF5A, KIF5B, and KIF5C), stand out as crucial players in anterograde transport, with disruptions leading to neurodegenerative conditions like Alzheimer’s and hereditary spastic paraplegia." (PMID 39507380, 2024).
epilepsy (4 papers, 2020 to 2024). A brain disorder characterized by episodes of abnormally increased neuronal discharge resulting in transient episodes of sensory or motor neurological dysfunction, or psychic dysfunction. "This was the first in‐frame deletion as well as the first reported variant within the ATP‐binding domain of the KIF5C protein, which caused severe symptomatic epilepsy, seizures, ID, brain atrophy, and psychomotor retardation." (PMID 38525108, 2024). "In particular, recurrent de novo variants at the E237 residue of the KIF5C protein have been associated with a syndrome characterized by intellectual disability, autistic traits, epilepsy, frontal cortical dysplasia and dysmorphic facial features." (PMID 37756604, 2023). "Here, we focus on unc-116, the Caenorhabditis elegans ortholog of the KIF5C kinesin-1 heavy chain gene that has been implicated in NDDs including intellectual disability, epilepsy and autism." (PMID 37756604, 2023). "The current study reported a novel heterozygous in‐frame deletion (c.265_267delTCA) in exon 3 of the KIF5C gene, which resulted in symptomatic epilepsy, seizures, ID, brain atrophy, and psychomotor retardation in a Chinese patient." (PMID 38525108, 2024). "Kinesin Family Member 5 C (KIF5C) mutation resulted in neurodevelopmental disorders, including epilepsy, language barrier, and brain malformations." (PMID 38347610, 2024). "The strongest evidence comes from recurrent de novo variants that alter E237 of KIF5C and are associated with a neurodevelopmental syndrome that includes epilepsy, intellectual disability, autistic features and absent language." (PMID 37756604, 2023).
Intellectual disability (4 papers, 2015 to 2025). "KIF16B, KIF4A, and KIF5C mutations were found in clinical samples, and patients showed varying degrees of intellectual disability." (PMID 40964093, 2025). "In addition to the identification of this specific KIF5C syndrome, a role for other KIF5C variants in autism and intellectual disability has been supported by analysis of large-scale sequencing studies, revealing a statistically significant enrichment of KIF5C de novo variants in people with NDDs." (PMID 37756604, 2023).
amyotrophic lateral sclerosis (3 papers, 2023 to 2025). Amyotrophic lateral sclerosis (ALS) is a neurodegenerative disease characterized by progressive muscular paralysis reflecting degeneration of motor neurons in the primary motor cortex, corticospinal tracts, brainstem and spinal cord. "Mutations in KIF5A, KIF5B and KIF5C are causes of neurological disorders such as amyotrophic lateral sclerosis (ALS)." (PMID 41290147, 2025).
brain malformations (3 papers, 2020 to 2024). "This was in addition to a de novo missense p.(Glu237Gly) variant in KIF5C, a gene in which pathogenic heterozygous variants cause cortical dysplasia with other brain malformations (CDCBM2, OMIM #615282)." (PMID 37946251, 2023). "KIF5C heterozygous missense mutations are associated with complex cortical dysplasia and other brain malformations [OMIM 615282]." (PMID 31989799, 2020).
cortical dysplasia (3 papers, 2016 to 2023). "Moreover, variants in KIF5A and KIF5C lead to spastic paraplegia (MIM#604187) and cortical dysplasia (MIM#615282), respectively." (PMID 27435318, 2016).
schizophrenia (3 papers, 2018 to 2021). A major psychotic disorder characterized by abnormalities in the perception or expression of reality. "The duplication of KIF5C in our patient may lead to increased expression of KIF5C in the brain and contribute to the pathogenesis of schizophrenia, which is distinct from the clinical symptoms caused by loss-of-function KIF5C pathogenic variants." (PMID 34659328, 2021).
glioma (2 papers, 2023 to 2025). A benign or malignant brain and spinal cord tumor that arises from glial cells (astrocytes, oligodendrocytes, ependymal cells). "KIF5C promotes glioma progression by enhancing cell proliferation, migration, and invasion through the AKT signaling pathway and cytoskeletal organization." (PMID 41356219, 2025). "Five genes (KIF5C, LINC00632, B4GALNT3, HIF3A, and RAD51L3-RFFL) show significant differential expression between primary and recurrent tumors, with four having established functional roles in glioma pathobiology." (PMID 41356219, 2025). "The identification of five genes (KIF5C, LINC00632, B4GALNT3, HIF3A, and RAD51L3-RFFL) with differential expression between primary and recurrent tumors provides critical insight into the molecular mechanisms driving recurrence, the key challenge in the management of IDH wild-type glioma." (PMID 41356219, 2025).
microcephaly (2 papers, 2024). A congenital or acquired developmental disorder in which the circumference of the head is smaller than normal for the person's age and sex. "In contrast, just over 20 mutations have been reported for KIF5C, which predominantly result in neurodevelopmental disorders, such as cortical development and microcephaly, likely through a key role in neuronal polarisation." (PMID 38309508, 2024). "To date, only two missense variants, including p.Glu237Val and p.Glu237Lys, located in the MBD of KIF5C have been reported, which cause MCD and microcephaly." (PMID 38525108, 2024).
prostate carcinoma (2 papers, 2024). A carcinoma that arises from epithelial cells of the prostate gland. "We did not observe changes to prostate cell phenotype or migration from KIF5B knockdown, yet KIF5C silencing significantly increased migration of prostate cancer cells." (PMID 39217195, 2024).
bacterial meningitis (1 paper, 2024). Inflammation of the membranes surrounding the brain and spinal cord due to a bacterial infection. "GPR68 and KIF5C, identified in bacterial meningitis co-expression analysis, had an area under the curve (AUC) of 1.00, while the AUC of OR52K2 and CCR5 is 0.883 and 0.698, respectively." (PMID 38347610, 2024). "The diagnostic value of GPR68, KIF5C OR52K2, and CCR5 were assessed in bacterial meningitis." (PMID 38347610, 2024). "In this study, CCR5, KIF5C, OR52P2P, OR52K2, and OR51R1P were co-expression with lncRNA AC091138.1 in bacterial meningitis specific co-expression networks." (PMID 38347610, 2024). "In bacterial meningitis patients, 8 co-expression relationships were constructed between 8 mRNAs (ACBD7, OR52K2, GPR68, SHISA4, KIF5C, OR52P2P, OR51R1P, and CCR5) and 1 lncRNA." (PMID 38347610, 2024). "Moreover, KIF5C, GPR68, and OR52K2, with higher AUC, may be potential diagnosis makers in bacterial meningitis." (PMID 38347610, 2024).
Cirrhosis (1 paper, 2014). A chronic disorder of the liver in which liver tissue becomes scarred and is partially replaced by regenerative nodules and fibrotic tissue resulting in loss of liver function. "In addition, KIF5C, MYH8, SETD2 and UNC13C mutations were only found in HCC patients in the absence of cirrhosis (0% vs. 11%, p = 0.036 for all four genes)." (PMID 24988079, 2014).
developmental arrest (1 paper, 2024). "All the data in this study supported the conclusion that p.Ser90del of KIF5C might cause severe developmental arrest and affect viability." (PMID 38525108, 2024).
developmental delay (1 paper, 2021). "Pathogenic mutations KIF5C are rare but cause abnormal cortical development and result in severe developmental delay, absent language, seizures, and abnormal behaviors in affected patients, indicating the critical role of KIF5C in the normal development of the cortex." (PMID 34659328, 2021).
esophageal squamous cell carcinoma (1 paper, 2024). Esophageal squamous cell carcinoma (ESCC) is a type of esophageal carcinoma (EC) that can affect any part of the esophagus, but is usually located in the upper or middle third. "Bioinformatics analysis showed that KIF5C is a direct target of miR-203, and overexpression of KIF5C partially offsets the tumor inhibitory effect of miR-203 on esophageal squamous cell carcinoma cells." (PMID 38172247, 2024).
osteosarcoma (1 paper, 2009). A usually aggressive malignant bone-forming mesenchymal neoplasm, predominantly affecting adolescents and young adults. "First, we examined the mRNA expression levels of KIF5B in three cancer cell lines(MCF-7, HeLa and U2OS osteosarcoma) and found it to be highly expressed in allthree cell lines when compared to other N-kinesins including KIF5A/KIF5C(Kinesin 1), KIF3A (Kinesin 2) and KIF1A (Kinesin 3)." (PMID 19242560, 2009).
Pachygyria (1 paper, 2022). Pachygyria is a malformation of cortical development with abnormally wide gyri with sulci 1,5-3 cm apart and abnormally thick cortex measuring more than 5 mm (radiological definition). "Further work addressing the neuronal cellular impact of improper KIF5C localization and activity will further elucidate how these mutations result in cortical malformations such as pachygyria." (PMID 36406756, 2022). "Patient mutations that have been identified in KIF5C have presented as pachygyria, characterized by broad folds and shallow grooves." (PMID 36406756, 2022).
scrapie (1 paper, 2021). A fatal disease of the nervous system in sheep and goats, characterized by pruritus, debility, and locomotor incoordination. "In our experiments we tested whether deletion of the molecular motor, KIF5C, would alter the tempo of scrapie spread and pathogenesis." (PMID 34372599, 2021). "The current study tested whether stereotactic inoculation in the striatum of KIF5C knock-out mice (Kif5c−/−) with 0.5 μL volumes of mouse-adapted scrapie strains 22 L or ME7 would result in an altered rate of prion spreading and/or disease timing." (PMID 34372599, 2021). "Knock-out mice depleted of KIF5C (Kif5c−/−) and C57BL/6 (B6) genetic controls were inoculated stereotactically with a small volume (0.5 μL) of either 22 L or ME7, two different mouse-adapted scrapie strains with different cellular tropisms." (PMID 34372599, 2021). "We infected Kif5c−/− and B6 mice with 22 L scrapie and allowed them to reach terminal disease to determine whether absence of the KIF5C motor could alter survival times, neuropathology or the distribution of PrPSc in brain at the end stage of disease." (PMID 34372599, 2021).
Uterine leiomyoma (1 paper, 2023). The presence of a leiomyoma of the uterus. "Although the physiologic roles of KIF5C in uterine smooth muscle are not known, its expression was reported to be upregulated in uterine leiomyomas." (PMID 35732928, 2023).
infection (13 papers, 2010 to 2024). The state of being infected such as from the introduction of a foreign agent such as serum, vaccine, antigenic substance or organism. "Following infection by P or M strains of PRV, similar levels of KIF5C protein were found in differentiated CAD cell total cytoplasmic extracts (PNS), float-up fractions and whole cell extracts." (PMID 32511265, 2020).
tumor (10 papers, 2014 to 2025). "As an important tumor suppressor, the level of Axin2 can be increased by KIF5C." (PMID 31844033, 2019). "Additionally, gene expression profiles and bioinformatics analysis revealed KIF5C to be a direct target of miR-203, and KIF5C overexpression partially counteracted the tumor inhibitory effects of miR-203 on EC cells." (PMID 31844033, 2019). "The level of Axin2, an important tumor suppressor, can be increased by inhibiting KIF5C." (PMID 31844033, 2019).
neurodegenerative disease (9 papers, 2010 to 2024). A disorder of the central nervous system characterized by gradual and progressive loss of neural tissue and neurologic function. "Our analysis of the AD interactome indicates that 14-3-3G interacts directly with tau (TAU) and other aggregate proteins, including ankyrin-3 (ANK3), plectin (PLEC), kinesin heavy chain 5C (KIF5C), and hexokinase (HXK1) —all of which play key roles in neurodegenerative-disease aggregation." (PMID 36555098, 2022).
cancer (7 papers, 2009 to 2024). A tumor composed of atypical neoplastic, often pleomorphic cells that invade other tissues. "In addition, the over-expression of the motor protein KIF5C in LNCaP cells, which is androgen regulated, also resulted in lysosome distribution changes to the perinuclear region of the cancer cells." (PMID 39217195, 2024). "Interestingly, only PLAU and KIF5C were elevated in cancer tissues compared to adjacent normal tissues." (PMID 31844033, 2019). "The data presented here suggest that KIF5B is implicated in several pathwaysinvolving lysosomes and that its highly expressed in all cancer cell lines tested,as compared to other N-Kinesins including KIF5A/KIF5C (Kinesin 1 family), KIF3A(Kinesin 2 family) and KIF1A (Kinesin 3 family)." (PMID 19242560, 2009).
neurodevelopmental disorder (5 papers, 2023 to 2024). A behavioral and cognitive disorder with onset during the developmental period that involves impaired or aberrant development of intellectual, motor, or social functions. "This study emphasized the importance of the KIF5C in intracellular cargo‐transport as well as germline variants leading to neurodevelopmental disorders." (PMID 38525108, 2024). "This study emphasized the importance of the KIF5C gene in intracellular cargo‐transport as well as germline variants that lead to neurodevelopmental disorders and might enable clinicians for timely and accurate diagnosis and disease management in the future." (PMID 38525108, 2024). "KIF5C is a kinesin-1 heavy chain that has been associated with neurodevelopmental disorders." (PMID 37756604, 2023).
KIF5C also shares sentences with these, for which no sentence is quoted: Alzheimer disease (6 papers); adenovirus infection (3); Huntington disease (3); breast carcinoma (2); HIV-1 infection (2); Lissencephaly (2); neuropathies (2); Salmonella Infections (2); virus infection (2); Anxiety (1); asthma (1); autism (1); axonal neuropathy (1); Bardet-Biedl syndrome (1); Brain atrophy (1); cardiac hypertrophy (1); cervical cancer (1); Chronic colitis (1); cognitive deficits (1); colon cancer (1); colorectal cancer (1); corneal disease (1); COVID-19 (1); cystinosis (1); diabetes (1); Diarrhea (1); dysplasia (1); Emery-Dreifuss muscular dystrophy (1); genetic disorders (1); Glucose intolerance (1).
A further 23 diseases each share a sentence with KIF5C in 1 paper.